ENSG00000245156 (novel transcript)
Gene: Long non-coding RNA gene on chromosome 11 (66,269,832 to 66,278,525, reverse strand). Ensembl gene ENSG00000245156.
Gene Ontology:
Biological process: SRP-dependent cotranslational protein targeting to membrane, signal sequence recognition
Cellular component: signal recognition particle, endoplasmic reticulum targeting